CXCL11 (C-X-C motif chemokine ligand 11)
Diseases named in the same sentence as CXCL11 in open-access papers (continued):
Sharing a sentence is not in itself a finding about the gene and the disease.
tumor (continued). "Regarding CXCL11, its mRNA upregulation was associated with a better prognosis in several cancers, and PD-L1 blockade combined with an oncolytic vaccinia virus expressing CXCL11 in mouse models was shown to considerably decrease tumor burden and improve prognosis." (PMID 38067341, 2023). "Similarly, CXCL11, CXCL12, and CXCL13 encoded the C-X-C motif chemokine ligands, critical regulators of tumor progression in many cancers." (PMID 37537613, 2023). "CXCL11 exhibits potent anti-tumor activity in vivo by promoting CD8+ T lymphocyte infiltration." (PMID 37547756, 2023). "Furthermore, we identified CXCL11 as a key factor, which positively promotes the progression of MM and correlate with macrophage M2-like polarization and tumor immune cells infiltration." (PMID 35568859, 2022). "In addition, some studies have demonstrated the regulatory effect of autocrine CXCL11 on PD-L1 by tumor cells." (PMID 36478746, 2022). "Regarding the cancer-promoting effect of CXCL11, existing research has shown that CXCL11 can directly affect the proliferation and migration of tumor cells or indirectly control tumor angiogenesis and regulate leukocyte infiltration to control tumor growth, metastasis, and lymphatic infiltration." (PMID 36478746, 2022). "Intratumoral delivery of CXCL11-expressing vaccina virus could induce an aggregation of adoptive T-cells in tumor tissues and prolong the survivals of tumor-bearing mice." (PMID 36145559, 2022). "Thus, LINC00152 knockdown in CAFs can reverse CXCL11 overexpression in CAF-induced tumor growth in a mouse model." (PMID 36435866, 2022). "In addition, the immunoregulatory effect of CXCL9, CXCL10, and the CXCL11/CXCR3 axis on tumor sites to promote antitumor immunity has been used as a new tumor therapeutic target." (PMID 35754838, 2022). "Interestingly, the majority of tumor cells tested (4 out of 5) showed increased toxin-induced cell death in the presence of either CXCL12 or CXCL11." (PMID 36539774, 2022). "CXCL10, CXCL11/CXCR3 axis can be used as the target of tumor immunotherapy." (PMID 35432485, 2022). "The expression levels of CXCL2, CXCL10 and CXCL11 were related to tumor stage." (PMID 35181719, 2022). "CXCL11 has various functions in the tumor microenvironment, such as suppressing angiogenesis, affecting cell proliferation, stimulating fibroblast directed carcinoma invasion, enhancing adhesion properties, inhibiting M2 macrophage polarization, and promoting the migration of certain immune cells." (PMID 36544484, 2022). "Another chemokine involved in the control of tumor progression is CXCL11." (PMID 36539774, 2022). "The collective evidence therefore suggest that SPATA2 over-expression is associated with a non-T-cell-inflamed TME in CRC, and that SPATA2 might mediate T cell exclusion by inhibiting the production of CXCL9, CXCL10, and CXCL11 from tumor cells." (PMID 36531014, 2022). "However, the results showed that CXCL11 expression was negatively related to tumor purity in all 33 cancers." (PMID 35935945, 2022). "The tumour volume of MDA-MB-231 cells was increased by 4-fold compared to the volume of MDA-MB-231 cells treated with conditioned medium from senescent HUVEC transfected with CXCL11 siRNA (p < 0.05)." (PMID 36059680, 2022). "In vivo, LINC00152 knockdown in CAFs inhibited HCC tumor growth in a mouse model, which could be reversed by CXCL11 overexpression in CAFs." (PMID 36435866, 2022). "We have now analyzed CXCL12 and CXCL11 for combined effects on tumor progression." (PMID 36539774, 2022). "Moreover, the correlations among CXCL11 expression, prognosis, mismatch repair, tumor mutation burden (TMB), microsatellite instability (MSI), tumor microenvironment, and immune-related genes were evaluated." (PMID 35935945, 2022). "We further identified CXCL11 not only a prognostic indicator but may also reflect immune status by influencing the recruitment of M2 macrophages, promoting tumor cell proliferation." (PMID 35568859, 2022).
tumor (continued). "Hence, we analyzed the relationships between the signature and TIP-related genes, and the results showed that cold tumor genes such as CXCL2 and CCL20 and hot tumor genes such as CXCR3, CXCL11, and PDCD1 were upregulated in the high-risk group in both cohorts." (PMID 35938001, 2022). "Moreover, high expression levels of CXCL10 and CXCL11 were associated with better PFI and early tumor stage in patients with CRC." (PMID 36003333, 2022). "To assess whether the combined effects of CXCL12 and CXCL11 on tumor cell invasion involve MMPs as an intermediate, we focused on the gelatinases MMP-2 and MMP-9, which represent known targets of CXCL12 and CXCL11." (PMID 36539774, 2022). "The existence of such combined influences is nevertheless likely and might eventually render further complexity to the crosstalk of CXCL12 and CXCL11 in tumor progression." (PMID 36539774, 2022). "In addition, CXCL11 binds to CXCR7, which is associated with cell invasiveness and reduced apoptosis of tumor cells." (PMID 36479091, 2022). "Proteins associated with tumor regression including granzyme A (GZMA) and Th1 markers such as the C-X-C motif chemokine ligand family (CXCL9, CXCL10, CXCL11) and interferon gamma (IFNG) mirrored the checkpoint inhibitor decreases seen in tissue during single agent pembrolizumab therapy." (PMID 36572780, 2022). "CXCL11 also promotes T cell chemotaxis and plays a role in anti-tumor immunity." (PMID 35269786, 2022). "In vivo, LINC00152 knockdown in CAFs inhibited tumor growth in a mouse model, which could be reversed by CXCL11 overexpression in CAFs." (PMID 36435866, 2022). "The expression of cytokines/chemokines is essential for attracting immune cells, suggesting that tumor infiltrating immune cells might be different in the CXCL11‐positive and CXCL11‐negative groups." (PMID 34047476, 2021). "We found that treatment with SHP099 led to increased expression of three CXCR3 ligands, the chemoattractant cytokines CXCL9, CXCL10 and CXCL11 specifically in tumor cells in co-culture, with CXCL10 showing the most significant upregulation and magnitude of expression." (PMID 33446805, 2021). "As CXCL11 was correlated with antitumor immunity, we aimed to identify the differentially expressed genes and enriched biological pathways mediated by CXCL11 in the tumor immune microenvironment." (PMID 33777950, 2021). "However, the possibility remains that in vivo CXCL11 is produced by other cells present within the tumour microenvironment." (PMID 33925140, 2021). "CCR5-CCL5 axis was induced to enhance NK cell infiltration in tumor tissue, and CXCR3 on NK cells also could interact with CXCL9, CXCL10, and CXCL11 from tumor cells." (PMID 33918941, 2021). "These in vitro findings were then confirmed by in vivo investigations that CAFs increased the number of tumor metastases in the mice bearing Huh-7 cell-derived tumors; when CXCL11 was silenced, the effects of CAFs on tumor progression were significantly attenuated." (PMID 33707417, 2021). "Furthermore, we discovered a relationship between CXCL11 expression and tumor immune microenvironment (TIM`E), including cytotoxic cells, neoantigen load, and immune checkpoint blockade (ICB)." (PMID 34047476, 2021). "Similar to CXCL10, CXCL11 may play anti-tumor or pro-tumor functions depending on the tissue context." (PMID 34200459, 2021). "Additionally, CXCL9 and CXCL10 are also expressed by M1-polarized TAMs and CXCL11 can be found on tumor vasculature." (PMID 34203660, 2021). "Importantly, the clinical examination of CXCL11 in tumor tissues or serum is more feasible than applying the steps necessary for calculating the HRD score, and the prediction accuracy of upregulated CXCL11 is even better than the HRD score itself." (PMID 34047476, 2021). "Additionally, some other chemokines controlling T lymphocyte homing to peripheral tissues, such as CCL5, CXCL9, CXCL10, and CXCL11, were also highly expressed in tumours containing large numbers of tumour HEVs." (PMID 33917287, 2021).
tumor (continued). "Likewise, CAFs promoted tumor migration in orthotopic models, as shown by an increased number of tumor nodules, whereas CXCL11 silencing triggered a decrease of it." (PMID 33707417, 2021). "Furthermore, the differential status of the tumor immune microenvironment in different groups of COAD patients determined by CXCL11 mRNA expression patterns was validated by CIBERSORT." (PMID 33777950, 2021). "Additionally, 968 increases the infiltration of CD3+ T cells into tumors, possibly through enhancing the secretion of CXCL10 and CXCL11 by tumor cells." (PMID 34944392, 2021). "Additionally, tumor-associated macrophages (TAMs) characteristic cytokines such as CXCL10 and CXCL11 were significantly differentially expressed." (PMID 34552581, 2021). "Similarly, a vaccinia virus expressing the chemokine CXCL11 or IL15Rα enhanced the anti-tumor activity of CAR T cells in solid tumors." (PMID 33801359, 2021). "Furthermore, we found upregulation of CXCL11 expression in tumor tissue compared with adjacent normal tissue in the COAD single-cell RNA-seq datasets GSE146771, and CXCL11 expression was positively correlated with PD-L1 (r = 0.66, P < 0.001)." (PMID 33777950, 2021). "As a consequence, suppression of VEGF signalling pathway by the treatment with sunitinib in tumour-bearing mice led to pronounced upregulation of CXCL10 and CXCL11 in tumour blood vessels, accompanied by a robust increase in the infiltration of leucocytes in tumours." (PMID 33917287, 2021). "In addition, CXCL10, CXCL9, and CXCL11 production is induced in the tumor microenvironment, which recruits cytotoxic lymphocytes (CTLs) and reduces tumor angiogenesis, inducing further tumor death." (PMID 33807260, 2021). "In the tumor microenvironment, CXCL11 upregulation enhanced CD8+ T-cell recruitment." (PMID 33031059, 2020). "CXCL11 overexpression also significantly restored the tumor suppressor role of miR-548t-5p." (PMID 32341359, 2020). "Besides angiogenesis, CXCL11 was an important cytokine in the progression of inflammation to CRC and induced tumor-associated macrophages to infiltrate, which enhanced the proliferation and invasion of CRC cells and generated poor prognosis." (PMID 32351322, 2020). "The increase in mRNA encoding expression of CXCR3, CXCL9 and CXCL10 (not CXCL11) as chemotactic chemokines suggests their involvement in the trafficking of anti‐tumor immune cells to the tumor site." (PMID 32821382, 2020). "CEA-TCB-treated tumors displayed a clear upregulation of several pro-inflammatory cytokines and chemokines [MIPα (CCL3), CXCL10, CXCL13, CXCL9, IL-16, and I-TAC (CXCL11)], an increase in intra-tumor CD3+, CD4+, CD8+ T-cells that express high levels of 4-1BB, PD-1, and upregulation of GZMB." (PMID 33330050, 2020). "Next, we checked the expression of CXCL11 in tumor cells after treatment with DOC or L-OHP." (PMID 30744691, 2019). "Additionally, irradiation enhanced the homing of the antigen-specific T cells to tumor tissues via the increased release of CCL5, CXCL9, and CXCL11 from tumor cells." (PMID 31921127, 2019). "The results demonstrated that polyphenols induce CXCR3 expression on regulatory T cells and increases CXCR3 ligands (CXCL9, CXCL10, CXCL11) in tumor microenvironment, it may become an important regulator in the treatment of CRC." (PMID 30973890, 2019). "We therefore proposed that CXCL11 might be able to reset the tumor microenvironment by modulating CD8+ T cell accumulation." (PMID 30744691, 2019). "We therefore proposed that DOC-based chemotherapy may influence the production of CXCL11, which could possibly reset the tumor microenvironment by regulating CD8+ T cells migration." (PMID 30744691, 2019). "Interestingly, co-localization of immunofluorescence and immunohistochemistry of serial sections indicted that CXCL11 was mostly located within the tumor cells." (PMID 30744691, 2019).
tumor (continued). "However, similar to the present cellular model, chemokines such as CXCL9, CXCL10, CXCL11 secreted in an autocrine manner by tumor cells were considered to contribute to a pro-tumoral microenvironment." (PMID 30847302, 2019). "Our findings implied that irradiation induced the release of CCL5, CXCL9, and CXCL11, which may produce a positive chemoattractant gradient in the tumor microenvironment and facilitate the migration of adoptively transferred T cells into tumor tissues." (PMID 31921127, 2019). "Additionally, IFN- γ stimulated tumor cells to produce CCL5, CXCL10, and CXCL11, which further supports the notion that DCs will be attracted toward tumor." (PMID 31379812, 2019). "For instance, epigenetic reprogramming of genes expressing T helper (TH)-1 chemokines like CXCL9 and CXCL11 might increase CD8+ T cell infiltration into the tumor bed." (PMID 31126321, 2019). "Accordingly, we hypothesized that the combination of an OV expressing CXCL11 and α-PD-L1 antibody would be an ideal regimen to treat tumours." (PMID 28345650, 2017). "Also, levels of the three chemokines CXCL9, CXCL10 and CXCL11 were markedly higher, exclusively in Lebanese tumor tissue as compared to non-tumor breast tissue, making BC in this population prone to metastasis." (PMID 27857161, 2016). "Thus, the sunitinib-related inhibition of VEGF signaling results in up-regulation of chemokines CXCL10 and CXCL11 (chemoattractant for T-cells) in tumor vessels." (PMID 27589830, 2016). "CXCL11 binds to its cognate receptor CXCR3 overexpressed by the tumor cells, which could promote cell proliferation and migration." (PMID 24384839, 2013). "Recently, we have shown in an organotypic culture system (reconstruct) that migration of CTL derived from a CRC patient towards autologous tumor cells was mediated by chemokine receptor CXCR3 expressed by the T cells, and CXCL11 chemokine secreted by the autologous tumor cells." (PMID 21450101, 2011). "Finally, the correlation between CXCL10 and CXCL11 and tumor immune invasion was analyzed." (PMID 40129606, 2025). "However, CXCL10 and CXCL11 can also increase tumor proliferation and metastasis." (PMID 40129606, 2025). "Moreover, CXCL11 contributes to the promotion of cancer invasion driven by fibroblasts through enhancing cell adhesion and suppressing M2 macrophage polarization, thereby influencing tumor progression." (PMID 38791448, 2024). "M1 macrophages suppress tumor growth due to intrinsic phagocytic and enhanced anti-tumor inflammatory reactions, suggesting that CXCL11 may have a tumor-resistant function in the tumor microenvironment (TME) repolarizing pro-tumor M2 macrophages into anti-tumor M1 macrophages." (PMID 39548525, 2024). "Consequently, they suggested that CXCL11 expression could behave as a prognostic marker and as a marker of response to immunotherapy treatment in all types of neoplasm." (PMID 38396726, 2024). "In addition, we investigated whether the expression of angiogenic factors, such as vascular endothelial growth factor (VEGF), was suppressed in CXCL9- and CXCL11-expressing tumor tissues using IHC." (PMID 37218983, 2023). "Moreover, RNA-seq results showed that NAT10 promoted the transcription of multiple critical cytokines such as CXCL3 and CXCL8 and suppressed CXCL10, CXCL11 and so on, which are important for the recruitment of immune cells, angiogenesis, tumor microenvironment remodeling, and cancer progression." (PMID 37914704, 2023). "Moreover, M2 macrophage infiltration was abrogated by knockdown of CXCL11 in xenograft tumor." (PMID 35568859, 2022). "The observed combined effects of CXCL12 and CXCL11 on cell migration prompted us to determine further whether similar applies for cell invasion, a process more closely reflecting metastatic behavior of tumor cells." (PMID 36539774, 2022).
tumor (continued). "Besides, critical chemokine ligand family members (including CXCL1, CXCL2, CXCL5, CXCL8, and CXCL11), which involved in tumor growth regulation and metastasis and mediated the enrichment of CD8+ T cells into the TME, were upregulated in the high AI score subtype." (PMID 36245985, 2022). "In addition, CXCL10 and CXCL11 were closely related to CD8+ tumor-infiltrating lymphocytes, which may predict benefit from PD-1 blockade therapy." (PMID 34093667, 2021). "The mechanism underlying the function of CXCL11 in the tumor environment may explain its negative association with prognosis." (PMID 35087741, 2021). "From this perspective, CXCL11 may contribute to tumor progression." (PMID 33777950, 2021). "Additionally, increased CXCL11 levels measured in tumor tissue of patients treated with DOC suggests that CXCL11 may be involved in eliciting a systemic immune response in patients." (PMID 30744691, 2019). "In addition, ACKR3, formerly known as CXCR7, is a scavenger receptor for CXCL11 that may reduce the availability of CXCL11 in vivo and in the tumor bed." (PMID 31216755, 2019). "Also notable is a minimal change in expression of the chemokine CXCR3 but a significant increase in the expression of its ligands, CXCL10 and CXCL11, which are important in activating other signaling molecules that recruit immune cells for the general enhancement of anti-tumor pathways." (PMID 31795829, 2019). "This marked sensitivity of the immune C26 tumor microenvironment to corticosterone was also reflected by the correlation between anti-IL-6-induced decreased plasma levels of the hormone and increased mRNA levels of Cxcl9, Cxcl10, and Cxcl11 in food-restricted pre-cachectic C26-bearing mice." (PMID 27829137, 2016). "CD11b+Gr1+ secretion of CXCL11 may mediate effects on fibroblasts as well as tumor cells." (PMID 25629162, 2015). "Furthermore tumor-expressed CXCL9 was shown to be crucial for immune control of murine cutaneous fibrosarcomas while CXCL11 secretion by genetically modified mouse T cell lymphoma cells (EL4) led to increased infiltration of CD8+CXCR3+ T cells and subsequent tumor rejection." (PMID 23874342, 2013). "CXCR3, which is present on activated MO/MAs and on activated T cells, binds several rIFN-γ1b- induceable chemokines, including CXCL9/Mig, CXCL10/IP-10, and CXCL11/I-TAC These chemokines might facilitate recruitment of activated leukocyte subsets to the tumor site." (PMID 16603073, 2006). "This process requires the production of appropriate chemokines by the endothelial cells and tumor stroma, namely CXCL9, CXCL10, CXCL11, and CCL5." (PMID 41008910, 2025). "CXCL11 has been shown to recruit CD8+ T cells for tumor cell killing, while the traditional view suggests that downregulating PD-L1 in PCa exerts anti-tumor effects." (PMID 41154598, 2025). "While the −SG diet induces tumor cell secretion of chemokines such as CCL5 and CXCL11 to promote CD8+ T cell recruitment, it concurrently increases tumor lactate production, which stabilizes PD-L1 via lactylation." (PMID 41303712, 2025). "Then, it is revealed that Plac1+ tumor cells recruit CD4+ T cells via CXCL11/CXCR3 and induce Treg differentiation via PVR/TIGIT, which in turn activates the tumorigenic signaling of Plac1+ tumor cells via LTA/LTBR and forms a reciprocal protumor loop." (PMID 40056047, 2025). "Despite these factors, we found that lung macrophages isolated from lung biopsies taken at sites distant from the tumor exhibited corticosteroid sensitivity, as evidenced by reduced expression of CXCL9, CXCL10, and CXCL11." (PMID 41229420, 2025). "Through in vitro and in vivo experiments, we disclosed that NCD upregulates the TIME-GES genes CXCL10, CXCL11, EBI3, and FLT3LG, promotes CD8+ T cell activation and tumor infiltration, thereby inhibiting the growth of TNBC." (PMID 41293150, 2025). "Subsequently, we examined the mRNA levels of CCL5, CD274, CXCL10, CXCL11, and CCL2 in MDA‐MB‐231 and 4T1 cells and tumor tissues." (PMID 39585774, 2025).